COMMD9 (COMM domain containing 9)
Description:
Scaffold protein in the commander complex that is essential for endosomal recycling of transmembrane cargos; the commander complex is composed of the CCC subcomplex and the retriever subcomplex. May modulate activity of cullin-RING E3 ubiquitin ligase (CRL) complexes. May down-regulate activation of NF-kappa-B. Modulates Na(+) transport in epithelial cells by regulation of apical cell surface expression of amiloride-sensitive sodium channel (ENaC) subunits.
Synonyms: HSPC166; FLJ31106; C11orf55; LINC00610
Tractability: Antibody: its Gene Ontology location is reachable by antibodies, with high confidence. PROTAC: ubiquitination databases record sites on it; its protein half-life has been measured.
Gene: Protein-coding gene on chromosome 11 (36,269,284 to 36,289,449, reverse strand). Ensembl gene ENSG00000110442.
Subcellular location: Nucleus; Cytoplasmic vesicle
Subcellular location (Human Protein Atlas): Nucleoplasm; Cytosol; Golgi apparatus
Pathways (Reactome):
Immune System: Neutrophil degranulation
Metabolism of proteins: Neddylation
Gene Ontology:
Molecular function: protein binding
Biological process: endocytic recycling
Cellular component: cytoplasmic vesicle; nucleoplasm; nucleus; protein-containing complex; endoplasmic reticulum membrane; endosome membrane; extracellular region; ficolin-1-rich granule lumen; secretory granule lumen
Genetic constraint (gnomAD): Loss-of-function variants: 18 observed, 17.61 expected, observed/expected ratio (o/e) 1.02, 90% interval 0.7 to 1.51. The upper end of that interval is the gene's LOEUF score, 1.51, which puts it in group 6 of 6, group 1 being the genes least tolerant of losing a copy. Missense variants: 211 observed, 228.86 expected, observed/expected ratio (o/e) 0.92, 90% interval 0.82 to 1.03. Synonymous variants: 95 observed, 94.07 expected, observed/expected ratio (o/e) 1.01, 90% interval 0.85 to 1.2.
Homologues: Orthologues: chimpanzee COMMD9 (99% identical), dog COMMD9 (95% identical), pig COMMD9 (93% identical), guinea pig COMMD9 (90% identical), mouse Commd9 (90% identical), rat Commd9 (89% identical), rabbit COMMD9 (78% identical), tropical clawed frog commd9 (67% identical), zebrafish commd9 (61% identical), macaque COMMD9 (58% identical).
Diseases named in the same sentence as COMMD9 in open-access papers:
COMMD9 is named in the same sentence as 8 diseases in open-access papers, as found by Europe PMC text mining. Sharing a sentence is not in itself a finding about the gene and the disease. The quoted sentences say what the papers report.
lung carcinoma (4 papers, 2020 to 2024). "On the contrary, COMMD9 acts as a carcinogen in lung cancer." (PMID 34943955, 2021). "COMMD9, unlike other COMMD proteins, was found to be overexpressed in several lung cancer cell lines." (PMID 34943955, 2021).
non-small cell lung carcinoma (4 papers, 2021 to 2024). A group of at least three distinct histological types of lung cancer, including non-small cell squamous cell carcinoma, adenocarcinoma, and large cell carcinoma. "COMMD9 can inhibit cell proliferation and migration, arrest cell cycle at G1/S transition, and induce autophagy in non-small cell lung cancer cells." (PMID 35399735, 2022). "COMMD9 can inhibit cell proliferation and migration, and induce autophagy in non-small cell lung cancer cells." (PMID 35399735, 2022). "COMMD9 is also reported to have an inhibitory effect on the expansion and migration of non-small-cell lung cancer cells, blocking cells in the G1/S phase and inducing autophagy." (PMID 36092163, 2022). "The mRNA expression levels of COMMD3, COMMD4, COMMD5, COMMD6, and COMMD8 were also significantly downregulated in non-small cell lung cancer (NSCLC) cell lines, whereas COMMD9 was up-regulated and promotes the development of NSCLC by interacting with the TFDP1/E2F1 through the COMM domain." (PMID 33768002, 2021).
Sepsis (2 papers, 2023 to 2025). Sepsis is defined as life-threatening organ dysfunction caused by a dysregulated host response to infection. "We identified COMMD9, CSF3R, and NUB1 as potentially biologically relevant genes and diagnostic markers for sepsis." (PMID 37449204, 2023). "We therefore investigated the relationship between COMMD9, CSF3R, and NUB1 expression and the infiltration of immune cells in specimens from patients with sepsis and healthy controls." (PMID 37449204, 2023). "We uncovered 50 DEGs between the cohorts that we further analyzed, resulting in prioritization of COMMD9, CSF3R, and NUB1 as potential biomarkers to diagnose sepsis." (PMID 37449204, 2023). "We found that, compared with normal samples, the expression levels of COMMD9 and CSF3R were all significantly down-regulated in samples from patients with sepsis compared to control samples." (PMID 37449204, 2023). "Recent similar studies have effectively utilized SVM-RFE to identify COMMD9, CSF3R, and NUB1 as potential biomarker genes for predicting sepsis, uncovering new mechanisms in disease pathogenesis that may offer opportunities for therapeutic intervention." (PMID 40535544, 2025). "Only three genes were identified by both of the approaches: COMMD9, CSF3R, and NUB1, suggesting these genes may be involved in sepsis diagnose." (PMID 37449204, 2023). "This study is the first to propose and verify differential expression of COMMD9, CSF3R, and NUB1 in patients with sepsis, and ROC analysis confirmed that they may be useful as diagnostic biomarkers." (PMID 37449204, 2023). "Ultimately, we identified COMMD9, CSF3R, and NUB1 as genes that could potentially be used as biomarkers to predict sepsis, which we confirmed by ROC analysis." (PMID 37449204, 2023). "In this study, we found that COMMD9, CSF3R, and NUB1 regulate immune cell infiltrate during sepsis, and we speculate that the activity of these genes may influence the development of sepsis." (PMID 37449204, 2023). "We identified three genes, COMMD9, CSF3R, and NUB1, that were differentially expressed in sepsis compared to non-pathological specimens, and we correlated the differential expression of these genes with the immune cell composition of immune infiltrate." (PMID 37449204, 2023).
cancer (3 papers, 2020 to 2023). A tumor composed of atypical neoplastic, often pleomorphic cells that invade other tissues. "COMMD5 alterations have been detected in eight cancer studies, compared to four for COMMD2 and only one for COMMD9." (PMID 33768002, 2021).
COMMD9 also shares sentences with these, for which no sentence is quoted: hepatocellular carcinoma (1 paper); pancreatic ductal adenocarcinoma (1); renal cell carcinoma (1); tumor (1).